TGFBI (transforming growth factor beta induced)
Diseases named in the same sentence as TGFBI in open-access papers (continued):
Sharing a sentence is not in itself a finding about the gene and the disease.
tumor (continued). "In vitro studies have shown an association of TGFBI in maintaining microtubule stability and inhibiting tumorigenicity and tumor angiogenesis." (PMID 25369402, 2014). "Earlier, our group presented evidence that TGFBI deficiency can lead to mutations, chromosomal fragmentation, and genetic instability, which in turn promotes tumor development." (PMID 22695319, 2012). "To identify the mechanism underlying the role of TGFBI in tumor cell response to chemotherapy, we transiently over-expressed TGFBI in the metastatic NSCLC cell line NCI-H1299, which has a low basal expression of this protein (H1299-TGFBIve)." (PMID 20509890, 2010). "Studies have shown that aberrant expression of TGFBI is associated with the development of a variety of cancers and may play a tumor-promoting or tumor-suppressing role in the tumor microenvironment." (PMID 39752341, 2025). "In the context of cancer, TGFBI has been associated with both tumor suppressor and promotion." (PMID 38514830, 2024). "In our previous research 9, we demonstrated that M2-like tumor-associated macrophages (TAMs) secrete TGFBI, promoting GBM growth through integrin αvβ5-Src-Stat3 signaling, emphasizing the significance of TGFBI in the immune microenvironment of GSCs under normoxic conditions." (PMID 39346536, 2024). "The risk score of each patient was calculated using the following formula based on their regression coefficient of the expression levels of these 3 markers: risk score = 0.003 × Hscore of FHL3 in tumor -0.006× Hscore of GGA1 in tumor +0.004× Hscore of TGFBI in stromal." (PMID 37258779, 2023). "CSMD2 has shown activity as a tumor suppressor and TGFBI has been shown to inhibit tumor cell invasion, where loss of these genes may lead to tumor progression." (PMID 35565354, 2022). "In addition to its function as tumor microenvironment regulating factor, genetic polymorphisms in TGFBI are positively associated with levels of insulin and body mass index in the Korean population." (PMID 33958649, 2021). "TGFBI deficiency predisposed mice to spontaneous tumor development." (PMID 33912443, 2021). "In addition to the dual role in tumor progression, the expression of TGFBI has also been associated with chemotherapeutic drug sensitivity." (PMID 33912443, 2021). "In this study, TGFBI expression was an indicator of the level of infiltration of CAFs, which represent the main component of the tumor stroma and are strongly associated with epithelial–mesenchymal transition, massive stromal cell infiltration, and poor cancer prognosis." (PMID 34671645, 2021). "Moreover, we analyzed the correlations between TGFBI and tumor stemness scores (RNAss, and DNAss), which are associated with tumor pathology and tumor dedifferentiation." (PMID 34671645, 2021). "Moreover, Expression of TGFBI (F = 6.34, P = 3.17E-04) was significantly associated with tumor stage." (PMID 32406866, 2020). "TGFBI is also overexpressed in our metastatic discovery set and has been shown to induce epithelial to mesenchymal transition as well as being associated with ccRCC tumor progression and poor prognosis." (PMID 32850445, 2020). "Additionally, the drug combination upregulated PINK1, IRF1, PPP1R15A, CRABP2, SCRN1, LIMA1, and TGFBI; all genes associated with tumor suppression functions in PCa." (PMID 29545934, 2018). "TGFBI knockout mice show increased spontaneous tumor growth and susceptibility to chemically induced skin tumors as compared to wild-type mice, suggesting a tumor-suppressor function." (PMID 28106769, 2017). "The loss of chromosomal integrity may explain the increased tumor tendency in the TGFBI knockout mice." (PMID 22949874, 2012). "The result demonstrated that TGFBI expression was significantly associated with stromal score (P < 0.001), immune score (P < 0.001), gender (P < 0.001), neoplasm histologic grade (P < 0.001), pathologic stage (P = 0.011), and person neoplasm cancer status (P < 0.001)." (PMID 32406866, 2020).
tumor (continued). "However, multiple studies report a causative tumor-promoting function of TGFBI." (PMID 25889002, 2015). "Accumulating evidence demonstrates that TGFBI displays dysregulated expression patterns across multiple malignancies, with its expression levels exhibiting strong correlations with tumor invasiveness and metastatic potential." (PMID 40430059, 2025). "Functional studies have demonstrated that TGFBI silencing significantly inhibits endothelial cell proliferation and vascular sprouting, whereas exogenous TGFBI treatment can reverse these effects, underscoring its pivotal role in tumor angiogenesis." (PMID 40430059, 2025). "Within the tumor microenvironment, TGFBI facilitates tumor angiogenesis and metastasis by remodeling the extracellular matrix and regulating immune cell infiltration." (PMID 41377395, 2025). "Some studies have reported a positive correlation between TGFBI expression and the polarization of macrophages toward the M2 subtype, which in turn promotes tumor progression and metastasis." (PMID 38297161, 2024). "Although previous reports have highlighted the dual nature of TGFBI, acting both as a tumor suppressor and a promoter, accumulating evidence underscores its significant effects in driving tumor progression." (PMID 38514830, 2024). "Consistently, we observed preferential expression of TGFBI in tumor cells of hypoxic regions in GBM specimen, suggesting hypoxia induced TGFBI expression." (PMID 39346536, 2024). "We analyzed the expression of TGFBI in tumor tissues and corresponding normal tissue specimens from RCC patients using western blot." (PMID 39068456, 2024). "Building upon our prior research on the impact of TGFBI secreted by TAMs on GSCs in normoxic conditions, our current investigations that integrate the critical tumor niche components of hypoxia and the immune microenvironment are essential." (PMID 39346536, 2024). "The two more-abundant proteins in both analyzed tumor regions were transforming growth factor-beta-induced protein ig-h3 (beta ig-h3) and guanine nucleotide binding protein G(i) subunit alpha 2 (Galphai2)." (PMID 39195201, 2024). "To further confirm the role of the PI3K/AKT/mTOR/HIF-1α signaling pathway in TGFBI-mediated tumor promotion, we used the AKT activator SC79 to treat 786-O cells transfected with TGFBI siRNA." (PMID 39068456, 2024). "Analysis of an independent transcriptome database (GSE86237) also indicated elevated TGFBI expression in CD133+ tumor cells compared to the tumor bulk." (PMID 39346536, 2024). "The detailed mechanism on the involvement of TGFBI in regulating tumor microenvironment and stemness requires further study." (PMID 38514830, 2024). "Transforming growth factor beta induced (TGFBI) takes involved in some of physiological processes, for example growth of the tumor, differentiation, and metastasis." (PMID 37205191, 2023). "TGFBI is implicated in growth and dissemination of tumor cells, given that TGFBI could suppress cellular adhesion and keep survival course of tumor cells via DNA damage (chemoresistance), which is also a critical pro‐angiogenic factor (growth or tumor progression)." (PMID 37434432, 2023). "TGFBI has been reported to be both tumor-suppressive as well as tumor-promoting in multiple cancers depending on the cancer progression." (PMID 37835457, 2023). "VSIG4 was indicated to be a characteristic marker for tumor-associated macrophage populations, while TGFBI and P4HB were showed to be broadly expressed in ccRCC tumor and its immune microenvironment." (PMID 37035174, 2023). "Three genes (DTNA, STC2, and TGFBI) were differentially expressed between HNSCC tumor tissue and normal tissue, and STC2 and TGFBI were significantly up-regulated in tumor tissue, which was consistent with the analysis results." (PMID 37964257, 2023).
tumor (continued). "The secreted ECM protein transforming growth factor beta induced (TGFBI) was involved in activating this pathway, demonstrating the relevance of the tumor microenvironment for therapeutic responses in OC." (PMID 37370735, 2023). "TGFBI promotes tumor development in CRC and its silencing prevents both in vivo tumor growth and in vitro angiogenesis." (PMID 37816854, 2023). "Scissor_C1 interacted significantly with CAF, endothelial, and myeloid cells in the tumor microenvironment, specifically through highly expressing TGFBI (Batlle and Massagué, 2019)." (PMID 37091977, 2023). "As we can see, the macrophage-expressed VSIG4 in lymph node was higher than that in ccRCC tumor and adjacent normal kidney, whereas the epithelium-expressed TGFBI and P4HB in ccRCC tumor were higher than those in adjacent normal kidney." (PMID 37035174, 2023). "TGFBI is an extracellular matrix related oncogene that can lead to a significant enhancement of glycolysis for invasive tumor phenotype." (PMID 35505422, 2022). "Further research clarifying the functional consequence of TGFBI suppression on B cell fate and the impact on tumor microenvironment reshaping is warranted." (PMID 35267594, 2022). "CD14+ TGFBI+ M0‐like TAMs compose the greatest proportion of total TAMs and are related to tumor angiogenesis, hypoxic necrosis, and tumor necrosis factor signaling and PI3K–AKT signaling pathways." (PMID 35634956, 2022). "Transforming growth factor-beta-induced protein ig-h3 (TGFBI) is an extracellular matrix molecule involved in various aspects of tumorigenesis, including tumor progression, angiogenesis and metastasis." (PMID 35454164, 2022). "TGFBI participates in various physiological processes, including differentiation, tumor progression, and metastasis." (PMID 35083181, 2022). "On the other hand, it has been shown that reduction of TGFBI in the tumour microenvironment by downregulation of TGFBI using siRNA or blocking monoclonal antibody can reduce tumour aggressiveness." (PMID 34548635, 2022). "In the current work, we elaborated on the molecular and signaling mechanism of TGFBI mediating TAMs pro-tumor effect on GSCs and tried to explore the potential application of TGFBI as the index of TAM functionality and tumor burden in the clinical background." (PMID 35673564, 2022). "Disruption of TGFBI-integrin αvβ5 signaling attenuated the tumor-promoting effect of TAMs and extended mice survival time, indicating this pathway as an attractive therapeutic target for GBM." (PMID 35673564, 2022). "Knocking down TGFBI by shRNA largely abrogated the tumor-supportive effect of TAMs compared to shNT." (PMID 35673564, 2022). "Targeting TGFBI in established lesions functionally reprogrammed F4/80 macrophages in tumor microenvironment." (PMID 36463238, 2022). "Tumor growth of PDAC cells with TGFBI depletion was significantly reduced and the amount of Ki67-positive protein was reduced as well, even though the effect was moderate." (PMID 35954398, 2022). "Although further investigation is needed to elucidate the functional role of TGFBI in the pathogenesis of eBL, the silencing mechanism identified in our study is common to a broad spectrum of cancers in which TGFBI acts as a tumor suppressor." (PMID 35267594, 2022). "Tumor expression of TGFBI, IGFBP3, and CHI3L1 were positively correlated with PDGFD and PDGFRB expression in TCGA LGG dataset, respectively." (PMID 34539622, 2021). "We also compared TGFBI expression between these TCGA tumor tissues and the corresponding normal tissues in the GTEx database, which showed that TGFBI was upregulated in 19 types of cancer tissues and downregulated in three types compared to normal tissues." (PMID 34671645, 2021). "Another study suggested that TGFBI possesses both tumor suppressor and promoter function depending on the tumor microenvironment (Ween, Oehler & Ricciardelli, 2012)." (PMID 33987033, 2021).
tumor (continued). "RNA-seq data also demonstrated that several genes related to adoptive immune systems which have pro-tumor action, such as TGFβ2, TGFBI, TGFBR1, TGFBR3, PLAU, IL-1β, and IL-33 are higher in Pn-positive cells than Pn-negative cells." (PMID 34680221, 2021). "The overall and progression-free survival was lower for patients whose CRC tumours had high TGFBI staining in a clinically well-annotated TMA compared with those with low levels of TGFBI, as determined by Kaplan–Meier survival analysis." (PMID 34887515, 2021). "Some components repelled certain cell types, for example, TGFBI, which decreased cell attachment of fibroblasts, and lumican and tenascin C, which reduced attachment of tumor cells." (PMID 34884982, 2021). "Some studies have revealed that TGFBI plays a role in various types of cancer, leading to tumor progression or inhibition by regulating angiogenic activity." (PMID 33958649, 2021). "Thrombospondin 1 (THBS1) (3.26-fold; p-value ≤ 0.05) which was significantly overexpressed in OKF6/TERT1-Shammah cells has been documented to be elevated in OSCC specimens induced by TGFBI which further promotes tumor migration and invasion." (PMID 33931671, 2021). "Cell adhesion of ECM proteins including collagen, fibronectin, and laminin is mediated by TGFBI and its function was widely investigated in various tumor progression." (PMID 34795689, 2021). "Then, we examined TGFBI effects in vivo using the CAM tumor model and an orthotopic mouse model of liver metastasis formation." (PMID 33408771, 2021). "As an important protein, TGFBI was widely studied in malignant progression, which was suggested to play an important role both in immune response and tumor immune microenvironment." (PMID 34035220, 2021). "Treatment of orthotopic mouse HGSOC tumors with an anti-TGFBI antibody reduced peritoneal tumor size, increased tumor monocytes, and activated β3-expressing unconventional T cells." (PMID 34561272, 2021). "Transforming growth factor-beta-inducible gene-h3 (TGFBI) is a secreted protein and possess tumor suppressor function." (PMID 33987033, 2021). "In recent years, a number of studies have shown that TGFBI is closely related to tumor growth, invasion, metastasis, and drug responses." (PMID 34671645, 2021). "In malignant diseases, TGFBI appears to have either tumor-suppressing or tumor-promoting roles, with reports that suggest that TGFBI can mediate cancer cell invasion and metastasis, and can enhance cancer cell extravasation." (PMID 34686725, 2021). "TGFBI is a matricellular protein-coding gene that plays an important role in tumor angiogenesis (Fico and Santamaria-Martínez, 2020), which was up-regulated in the liver and kidney of gayal with log2 fold changes of 1.34 and 1.45, respectively." (PMID 35087567, 2021). "To compare TGFBI expression between tumor and normal tissues, we applied TIMER2 to analyze TGFBI expression in various cancer types of TCGA." (PMID 34671645, 2021). "We have shown that TGFBI produces antiangiogenic activity in endothelial cells through direct interactions with αvβ3 integrin, leading to tumor inhibition." (PMID 33958649, 2021). "We also investigated the associations of TGFBI expression with tumor microenvironment (TME) components, immune cell infiltration, tumor mutational burden (TMB), and microsatellite instability (MSI), along with the TGFBI genetic alteration types." (PMID 34671645, 2021). "Our results emphasize that TGFBI expression is closely related to tumor cells, immune cell infiltration, and TME components, affecting cancer prognosis." (PMID 34671645, 2021). "We further evaluated the difference in TGFBI protein expression between the tumor tissues and normal tissues in the CPTAC database using UALCAN tools." (PMID 34671645, 2021). "Transforming growth factor-beta-induced (TGFBI) protein has important roles in tumor growth, metastasis, and immunity." (PMID 34671645, 2021).
tumor (continued). "Summary above we found TGFBI expression was significantly correlated with tumor purity in ccRCC, which suggested that TGFBI played an important role in immune infiltration in ccRCC." (PMID 32406866, 2020). "In order to evaluate the effects of TGFBI deletion in the tumour immune landscape, we first used the cibersort software." (PMID 33080107, 2020). "Our findings reveal that TGFBI plays an important role in tumour angiogenesis, thereby affecting tumour hypoxia and immune cell infiltration, which then ultimately generates a permissive microenvironment for CSCs and metastasis." (PMID 33080107, 2020). "Combining the literature review with this study, we believed that TGFBI played an important role in many events during immune response and tumor immune microenvironment." (PMID 32406866, 2020). "To uncouple potential direct effects of TGFBI on cancer cells from those on the tumour vasculature, we added exogenous TGFBI to MMTV‐PyMT;TgfbiΔ/Δ cells in culture." (PMID 33080107, 2020). "To gain a better understanding of the pathways affected by the deletion of TGFBI, we performed RNA sequencing of wt and ko tumours." (PMID 33080107, 2020). "Our results indicate that basal tumours show higher TGFBI staining scores compared to luminal A tumours." (PMID 33080107, 2020). "Here TGFBI has been proposed to act as tumor suppressor as it is downregulated in tumor cells and as tumor promoter when expressed by peritoneal stroma cells." (PMID 32312959, 2020). "The comparative genomic loci of most human and mouse TGFβ axis genes, including TGFB1–3, TGFBR1–3, and TGFBI, were mapped ~20 years ago, which paved the way for numerous functional studies of individual TGFβ genes in tumor biology." (PMID 32605311, 2020). "In the present study, we show that deletion of the matricellular protein TGFBI is sufficient to normalise the tumour vasculature and mitigate hypoxia." (PMID 33080107, 2020). "In conclusion, these data indicate that TNC and TGFBI as constituents of the TAM secretome promote tumor cell migration." (PMID 32312959, 2020). "As a proof of principle, we found that tumor migration induced by rTGFBI and rTNC was blocked by neutralizing anti-TGFBI and anti-TNC antibodies." (PMID 32312959, 2020). "Since we had previously found that in MMTV‐PyMT tumours macrophages secreted high levels of TGFBI, we argued that it should be possible to induce tumour hypoxia by transferring wt macrophages into lethally irradiated mice bearing TgfbiΔ/Δ tumours." (PMID 33080107, 2020). "We then estimated the abundance of different immune cell types in tumours expressing high or low levels of TGFBI in the METABRIC cohort using cibersort." (PMID 33080107, 2020). "The result demonstrated that TGFBI expression was correlated with tumor purity in ccRCC, which indicated that TGFBI played an important role in immune infiltration in ccRCC." (PMID 32406866, 2020). "TGFBI promotes cell adhesion by interacting with different integrins, which, in turn, has been shown to play an important role in tumor progression in humans." (PMID 31277676, 2019). "Many researchers have studied the role of TGFBI in different kinds of tumor, with the findings suggesting that it has diverse functions." (PMID 31598162, 2019). "TGFBI has been shown to participate in differentiation, proliferation, tumor progression and metastasis." (PMID 31514337, 2019). "By doing so, we identified WNT5a, TGFBI, and SERPINE1, all recently associated with the GBM mesenchymal subtype and tumor invasion, as well as GDF-15, also known to be linked to GBM progression and poor prognosis." (PMID 31453379, 2019). "TGFBI has been shown to participate in various physiological processes, such as differentiation, morphogenesis, cell growth, inflammation, tumor progression and metastasis." (PMID 31514337, 2019). "The effect of TGFBI on tumor metastasis in vivo was evaluated using a tail vein tumor metastasis model." (PMID 31598162, 2019).